CD300LD (CD300 molecule like family member d)
Synonyms: CLM-5; CD300d; CMRF35A4; CLM-4; CMRF35-A4
Tractability: Antibody: UniProt places it where antibodies can reach, with high confidence; its Gene Ontology location is reachable by antibodies, with high confidence; UniProt predicts a signal peptide or a membrane-spanning region.
Gene: Protein-coding gene on chromosome 17 (74,579,365 to 74,592,283, reverse strand). Ensembl gene ENSG00000204345.
Subcellular location: Cell membrane
Pathways (Reactome):
Immune System: Immunoregulatory interactions between a Lymphoid and a non-Lymphoid cell
Gene Ontology:
Molecular function: protein binding; transmembrane signaling receptor activity
Biological process: immune response-activating signaling pathway
Cellular component: plasma membrane
Genetic constraint (gnomAD): Loss-of-function variants: 14 observed, 17.12 expected, observed/expected ratio (o/e) 0.82, 90% interval 0.54 to 1.28. The upper end of that interval is the gene's LOEUF score, 1.28, which puts it in group 5 of 6, group 1 being the genes least tolerant of losing a copy. Missense variants: 175 observed, 216.66 expected, observed/expected ratio (o/e) 0.81, 90% interval 0.71 to 0.92. Synonymous variants: 90 observed, 85.04 expected, observed/expected ratio (o/e) 1.06, 90% interval 0.89 to 1.26.
Homologues: Orthologues: chimpanzee CD300LD (97% identical), macaque CD300LD (69% identical), mouse Cd300a (29% identical). Paralogues in human: CD300LF (51% identical), CD300LB (45% identical), CD300E (39% identical), CD300C (36% identical), CD300H (35% identical), CD300A (34% identical), CD300LG (25% identical), FCMR (25% identical), FCAMR (23% identical), TREM2 (21% identical), PIGR (21% identical), TREML1 (21% identical), and 1 more.
Diseases named in the same sentence as CD300LD in open-access papers:
CD300LD is named in the same sentence as 9 diseases in open-access papers, as found by Europe PMC text mining. Sharing a sentence is not in itself a finding about the gene and the disease. The quoted sentences say what the papers report.
lung carcinoma (2 papers, 2019 to 2024). "Another candidate is CD300ld, which was discovered in an in vivo CRISPR-Cas9 screen and was shown to be increased in PMN-MDSCs involved in tumor progression in mouse models, as well as in human tissues from colon and lung cancers." (PMID 38391927, 2024).
melanoma (1 paper, 2024). A malignant, usually aggressive tumor composed of atypical, neoplastic melanocytes. "Clinical relevance analysis showed that human CD300ld is up‐regulated in various tumour types, with a significant correlation between high CD300ld signalling and poor patient survival outcomes in melanoma patients." (PMID 38205725, 2024).
pneumococcal infection (1 paper, 2022). Infections with bacteria of the species streptococcus pneumoniae. "Cd300ld presents no clear link with pneumococcal infection, but its encoded protein, an activating receptor in myeloid and mast cells, was downregulated in the blood of mice infected with Streptococcus suis." (PMID 35795182, 2022).
tumor (12 papers, 2024 to 2025). "Single‐cell transcriptome analysis further revealed that loss of CD300ld significantly alters the pro‐ and anti‐tumour cell composition and the related immune pathways, remodelling the TME from immune suppressive to immune active." (PMID 38205725, 2024). "In tumor‐bearing mouse models, CD300ld knockout significantly reduces PMN‐MDSC infiltration into tumors, enhances the activation and migration of CD8+ T cells, and reshapes the immunosuppressive microenvironment into an antitumor state." (PMID 41201063, 2025). "CD300ld plays a dual role in the functionality of PMN‐MDSCs: it governs their recruitment to the tumor site and their capacity to robustly inhibit immune effector cells." (PMID 38911064, 2024). "Their findings revealed that conditional knockout of CD300ld markedly hindered tumor progression postestablishment." (PMID 38911064, 2024). "shed light on the indispensable role of CD300ld in facilitating tumor‐mediated immune suppression in PMN‐MDSCs,1 which provided a new target for cancer immunotherapy." (PMID 38911064, 2024). "We also generated CD300ld humanised mice and demonstrated that the tumour promoting activity of Cd300ld is conserved between mouse and human." (PMID 38205725, 2024). "Mechanism investigation revealed that CD300ld is required for both the recruitment of PMN‐MDSCs to tumours and their suppression on T‐cell activity through STAT3–S100A8/A9 axis." (PMID 38205725, 2024). "Targeting CD300ld can reshape the tumor immune microenvironment by inhibiting the recruitment and inhibitory function of PMN‐MDSCs, resulting in broad‐spectrum antitumor effects." (PMID 38911064, 2024). "Recent studies identified CD300ld as tumor immune suppressor in the recruitment of PMN-MDSCs into tumors and its function to suppress T cell activation." (PMID 38890669, 2024). "Subsequently, it was found that significant anti‐tumor effects still existed when blocking CD300ld after tumor formation." (PMID 38911066, 2024). "CD300ld knockout (KO) significantly impairs tumour development in multiple syngeneic and spontaneous tumour models in a PMN‐MDSC‐dependent manner." (PMID 38205725, 2024). "The role of CD300ld in mediating immune suppression seems to be critical for both tumor development and progression." (PMID 38911064, 2024). "Therefore, CD300ld was identified as a key functional receptor for PMN‐MDSCs to promote tumor development." (PMID 38911066, 2024). "CD300ld was competitively blocked by the injection of CD300ld extracellular domain protein, presenting similarly to CD300ld deletion, and showed meaningful anti‐tumor cooperation with anti‐PD1, implying the potential of CD300ld to be a therapeutic target." (PMID 38911066, 2024). "Upon tumour bearing, CD300ld expression is up‐regulated in PMN‐MDSCs." (PMID 38205725, 2024). "Therefore, CD300ld deletion can reduce the immunosuppressive capacity of the tumor microenvironment." (PMID 38911064, 2024). "Targeting CD300ld could remodel the tumor immune microenvironment, resulting in a broad‐spectrum anti‐tumor effect." (PMID 38911066, 2024). "Notably, CD300‐ld expression was predominantly observed in neutrophils and was markedly increased following tumor implantation." (PMID 38911064, 2024). "CD300ld was identified as a top candidate for tumour favouring receptor." (PMID 38205725, 2024). "The tumor‐promoting role of CD300ld appears to be conserved between mice and humans, indicating that CD300ld could be a viable target for cancer immunotherapy in humans." (PMID 38911064, 2024). "Moreover, the expression level of CD300ld in tumor tissues was significantly greater than that in adjacent nontumor and normal tissues and correlated strongly with neutrophil infiltration and patient prognosis." (PMID 38911064, 2024). "The results showed that inducing CD300ld knockout after tumor establishment could significantly inhibit tumor development." (PMID 38911064, 2024).
tumor (continued). "CD300ld target shows good safety, conservation, anti‐tumor effectiveness, and synergism with the Programmed death‐1 target, which is expected to become a new ideal target for tumor immunotherapy." (PMID 38911064, 2024). "Comparative studies revealed that CD300ld knockout mice experienced a considerable decrease in tumor size relative to their wild‐type counterparts, underscoring the significance of CD300ld on neutrophils for tumor‐driven immune suppression." (PMID 38911064, 2024). "In tumor‐bearing mice, both tasquinimod treatment and CD300ld gene knockout inhibited PMN‐MDSC migration and reduced immunosuppressive effects, suggesting that drugs targeting CD300ld could exhibit comparable antitumor efficacy to those targeting S100A8/S100A9." (PMID 40452814, 2025). "CD300ld is a recently identified immune inhibitory receptor that is highly expressed on polymorphonuclear MDSCs (PMN‐MDSCs) and promotes tumor immune escape by regulating neutrophil recruitment and function." (PMID 41201063, 2025). "CD300ld is specifically expressed in normal neutrophils and is upregulated in PMN-MDSCs upon tumour-bearing." (PMID 38890669, 2024). "A recent study identified CD300ld as a critical immunosuppressive molecule present on PMN-MDSCs, contributing to tumor immune evasion." (PMID 38890669, 2024). "In summary, this study discovered the key functional receptor CD300ld on the surface of PMN‐MDSCs, which plays an important role in tumor immunosuppression." (PMID 38911066, 2024). "In conclusion, this study has identified CD300ld as a specific surface marker and a critical immune suppressor on PMN‐MDSCs to promote tumour progression." (PMID 38205725, 2024). "Through the work of Wang and colleagues, there is now a better understanding of the role of CD300ld as a key immune suppressor on PMN‐MDSCs, contributing to tumor immune evasion and offering a molecular basis for its targeting in cancer immunotherapy strategies." (PMID 38911064, 2024). "Blockage of CD300ld remodels the immune‐suppressive TME and shows anti‐tumour efficacy, as well as synergistic effects with immune checkpoint inhibitors, providing a promising target for cancer immunotherapy and other systemic inflammatory disorders where PMN‐MDSCs are implicated." (PMID 38205725, 2024). "Competitive blockade of CD300ld by its extracellular domain (ECD) inhibits the growth of established tumour in a way similar to CD300ld KO, and exhibits a significant anti‐tumour synergy effect with anti‐PD1, indicating that CD300ld can serve as a therapeutic target." (PMID 38205725, 2024). "CD300ld knockout mice confirmed that CD300ld deletion not only significantly inhibited the development of various secondary and primary tumor models but also had no significant impact on the normal development of the mouse body and immune system." (PMID 38911066, 2024). "In this study, CD300ld, a membrane protein molecule specifically highly expressed in neutrophils or PMN‐MDSC, was screened and identified, and this molecule is deeply involved in tumor progression." (PMID 38911066, 2024). "Given that the high levels of CD300ld expression are limited to PMN‐MDSCs, and these cells are substantially reduced in CD300ld KO mice tumours, the results further suggested the central roles of PMN‐MDSCs in the establishment of a tumour promoting microenvironment." (PMID 38205725, 2024). "In this study, the absence of immune cells lacking CD300ld was particularly noteworthy in tumor environments, implying that cells expressing CD300ld could be facilitators of tumor growth." (PMID 38911064, 2024).
cancer (5 papers, 2019 to 2025). A tumor composed of atypical neoplastic, often pleomorphic cells that invade other tissues. "The study has established a comprehensive mechanistic network and validated CD300ld’s role using both genetic knockout models and antibody blockade, further corroborating these findings in human cancer samples." (PMID 40695812, 2025). "Overall, this study highlights the potential of CD300ld as a target for cancer immunotherapy." (PMID 38911064, 2024).
infection (3 papers, 2019 to 2021). The state of being infected such as from the introduction of a foreign agent such as serum, vaccine, antigenic substance or organism. "CD300lf is necessary for infection of MNoV-susceptible RAW 264.7 and BV2 cell lines while both CD300ld and CD300lf are sufficient to confer susceptibility to cell lines from different species when ectopically expressed." (PMID 32251490, 2020). "We report that both CD300ld and CD300lf are sufficient for infection by diverse MNoV strains in vitro." (PMID 32251490, 2020). "Exploration of whether this particular cell type is permissive to infection by MNoV via alternate receptor CD300LD, is of future interest." (PMID 33705489, 2021). "Do other CD300 family members such as CD300ld contribute to infection?" (PMID 32251490, 2020). "Similarly, both CD300ld and CD300lf are sufficient for MNoVWU23, MNoVCR3, MNoVCR7, MNoVMNV3, and MNoVS99 infection." (PMID 32251490, 2020). "Injection of zebrafish larvae with MNV (genogroup V) yielded no productive infection, most likely due to the fact that the receptors CD300lf and CD300ld are not encoded by zebrafish." (PMID 31536612, 2019). "We also identify CD300lf-independent viral infection in the setting of extra-intestinal challenge in immunodeficient mice, suggesting a potential role for CD300ld or other receptors in this non-physiological infection route." (PMID 32251490, 2020). "Consistent with our prior findings, both CD300ld and CD300lf are sufficient for infection by MNoVCW3 as measured by expression of the MNoV non-structural protein NS6/7 by flow cytometry." (PMID 32251490, 2020).
CD300LD also shares sentences with these, for which no sentence is quoted: breast carcinoma (1 paper); colorectal cancer (1); prostate carcinoma (1).